HMGB1 (high mobility group box 1)
Diseases named in the same sentence as HMGB1 in open-access papers (continued):
Sharing a sentence is not in itself a finding about the gene and the disease.
thyroid cancer (continued). "In addition, HMGB1 is overexpressed in thyroid cancer patient samples and cell lines and acts as a positive regulator of autophagy." (PMID 33979394, 2021). "CircFOXM1 contributes thyroid cancer through miR-1179/HMGB1 signaling." (PMID 34290668, 2021). "However, HMGB1 expression and its function in mediating autophagy in thyroid cancer have been poorly elucidated." (PMID 31331356, 2019). "Thus ROS was sufficient for inducing HMGB1 translocation and sustaining autophagy in thyroid cancer cells." (PMID 31331356, 2019). "Additionally, knockdown of HMGB1 restored the accumulated 99mTcO4− of thyroid cancer cells xenograft after hunger treatment in nude mice." (PMID 31331356, 2019). "These preclinical results suggest that HMGB1-mediated autophagy regulating NIS degradation could be a potential target for radioiodide therapy in thyroid cancer." (PMID 31331356, 2019). "In the present study, we examined the expression of HMGB1 in various thyroid cancer cell lines and patient samples, HMGB1 involvement in autophagy, its influence on NIS degradation and iodide uptake of thyroid cancer cells and its relationship with ROS/AMPK/mTOR pathway." (PMID 31331356, 2019). "Thus HMGB1 was required for 131I uptake in HBSS-treated thyroid cancer cells." (PMID 31331356, 2019). "Thus HMGB1 reflected different clinicopathologic features in thyroid cancer." (PMID 31331356, 2019). "The expression of HMGB1 in thyroid cancer cells is involved in autophagy processes by regulating NIS degradation and iodide uptake of thyroid cancer cells; for this reason, it is deepened in the context of radioresistance." (PMID 40943211, 2025). "Chai and colleagues recently demonstrated that high-mobility group box 1 (HMGB1) protein, a regulator of autophagy and chromatin remodeling, is upregulated in human thyroid cancer samples and represses iodide uptake by promoting NIS degradation." (PMID 35682803, 2022). "For example, high-mobility group box 1 (HMGB1), a highly conserved DNA-binding protein known to influence autophagy, CSC survival, and EMT was recently found to play a role in thyroid cancer." (PMID 35846375, 2022). "Recent studies also show that HMGB1 is involved in positive regulation and maintenance of ferroptosis in acute myeloid leukemia (AML) cells and autophagy in thyroid cancer cells, also prevents necroptosis in AML cells 42-44." (PMID 32489453, 2020). "Here HMGB1 expression became up-regulated in samples derived from patients of PTC, FTC and thyroid cancer cell lines." (PMID 31331356, 2019). "Here the authors intended to identify the role of HMGB1 in Hank’s balanced salt solution (HBSS)-induced autophagy, explore NIS protein degradation through a autophagy-lysosome pathway in thyroid cancer cells and elucidate the possible molecular mechanisms." (PMID 31331356, 2019). "Our study implied that HMGB1 was directly involved in the positive regulation and maintenance of autophagy in HBSS-treated thyroid cancer cells, thereby promoting NIS degradation and lowering iodide uptake." (PMID 31331356, 2019). "For example, cytosolic HMGB1 mediates starvation-induced autophagy through the ROS/AMPK/mTOR signaling axis, regulating the degradation of the sodium/iodide symporter and contributing to radioiodine therapy resistance in thyroid cancer cells." (PMID 41465435, 2025). "The abundant presence of HMGB1 has been detected in thyroid carcinoma cells but not in benign thyroid nodules or adenomas, indicating its involvement in the onset and progression of thyroid cancer." (PMID 38313845, 2023). "Similar to HMGB1 expression, the levels of Beclin1 expression were high in thyroid cancer tissues, but not in tissues derived from thyroid adenoma, simple goiter or normal thyroid." (PMID 31331356, 2019). "Higher levels of HMGB1 expression were detected in thyroid cancer samples, but not in samples from thyroid adenoma, simple goiter or normal thyroid." (PMID 31331356, 2019).
thyroid cancer (continued). "Although these studies have enriched our understanding of the role of HMGB1 in regulating autophagy and autophagy-related chemoresistance in leukemic cells, its possible role in the regulation of NIS degradation and radioiodide therapy by autophagy in thyroid cancer cells is unknown." (PMID 31331356, 2019).
acute myeloid leukemia (18 papers, 2015 to 2025). Acute myeloid leukemia (AML) is a group of neoplasms arising from precursor cells committed to the myeloid cell-line differentiation. "Loss of HMGB1 inhibits lipid peroxidation, providing a new therapeutic strategy for patients with acute myeloid leukemia (AML)." (PMID 40959280, 2025). "In acute myeloid leukemia, released HMGB1 promotes the proliferation of AML cells by influencing TNF-α production and interleukin 1β (IL - 1β) secretion, which promotes the release of stem cell factors." (PMID 40969278, 2025). "Interestingly, in acute myeloid leukemia and in retinoblastoma cells, the induction of HMGB1 parallels a decreased expression of miRNA-34a, which targets HMGB1 mRNA, leading to reduced apoptosis and induction of autophagy." (PMID 32792960, 2020). "miR-181b increases drug sensitivity in acute myeloid leukemia via targeting HMGB1 and Mcl-1." (PMID 32309578, 2016). "In Acute Myeloid Leukemia (AML), miR-34 acts as a tumor suppressor gene by targeting high motility group box 1 (HMGB1), a DNA-binding protein that can repair DNA mismatch and regulate gene transcriptions." (PMID 36009551, 2022). "For example, iron generates hydroxyl radicals via the Haber-Weiss reaction and the Fenton reaction, which promote ROS formation, and acute myeloid leukemia (AML) cells induce ferroptosis in AML cells by increasing ROS levels via the HMGB1-regulated RAS-JNK/p38 signaling pathway." (PMID 38816377, 2024). "Acute myelogenous leukemia (AML) cells were also sensitised to treatment when miRNA-142-3p levels are increased, via repression of high mobility box group 1 (HMGB1), an autophagic promoter, and P-glycoprotein, a drug efflux pump." (PMID 31979312, 2020). "HMGB1, besides acting as a pro-inflammatory DAMP, has also been observed to be overexpressed in several human tumor types, playing an important role in cancer progression and prognoses, such as acute myeloid leukemia and other carcinomas." (PMID 39157201, 2024).
bacterial sepsis (18 papers, 2010 to 2026). "Specifically, GSDMD pores trigger lung inflammation via alveolar macrophage pyroptosis, induce hepatic high mobility group box 1 protein (HMGB1) release, perpetuate bacteremia, cause renal microthrombosis, and disrupt the blood-brain barrier." (PMID 42094003, 2026). "Pharmacological agents with anti-inflammatory properties, such as calycosin and propofol, have been shown to mitigate sepsis-induced AEC injury by inhibiting HMGB1-mediated activation of downstream inflammasomes and signaling pathways, thereby alleviating bacterial Sepsis-Associated ALI." (PMID 40842982, 2025). "High mobility group box 1 (HMGB1) assumes a crucial function in liver inflammation and cellular damage during bacterial sepsis." (PMID 39956880, 2025). "In bacterial Sepsis-Associated ALI, LPS promotes AEC inflammation and apoptosis via the HMGB1/receptor for advanced glycation end products (RAGE) pathway." (PMID 40842982, 2025). "Studies have previously demonstrated conferred resistance to bacterial sepsis upon antibody-mediated inhibition of HMGB1, and binding of LPS to HMGB1." (PMID 33546173, 2021). "As research progresses, it may become possible to design novel therapies specifically targeting HMGB1, HMGB3, and their associated pathways to alleviate the impact of bacterial Sepsis-Associated ALI." (PMID 40842982, 2025). "Moreover, genetic deletion of HMGB1 or neutralizing circulating HMGB1 confers protection in lethal endotoxemia and bacterial sepsis." (PMID 34093202, 2021). "Increased sputum levels of HMGB1, albeit of unknown cellular origin, are significantly associated with bacteremia, but not disease severity, indicative of a possible, albeit unproven, role for HMGB1 in promoting dissemination of the pneumococcus that possibly involves platelets." (PMID 33042161, 2020). "In bacterial sepsis, type 1 IFN also mediates infection-induced disseminated intravascular coagulation, by amplifying the release of high-mobility group box 1 (HMGB1) into the bloodstream, which markedly increases the pro-coagulant activity of TF." (PMID 32574107, 2020). "Piperine, an alkaloid present in black pepper (Piper nigrum L.), protected macrophages from pyroptosis and decreased IL-1β and HMGB1 release by suppression of ATP-induced AMPK activation, suggesting the potential of piperine to be a therapeutic agent against bacterial sepsis." (PMID 36588685, 2022). "Our data indicated that piperine could protect macrophages from pyroptosis and reduced IL-1β and HMGB1 release by suppressing ATP-induced AMPK activation, suggesting that piperine may become a potential therapeutic agent against bacterial sepsis." (PMID 27812336, 2016).
multiple myeloma (18 papers, 2014 to 2025). "On the other hand, once HMGB1 is decreased, the mTOR pathway is activated to suppress autophagy and trigger apoptosis, increasing the susceptibility of myeloma cells to dexamethasone (Dex)." (PMID 37046991, 2023). "In multiple myeloma cells, HMGB1 was found to associate with the lncRNA MALAT-1 in a pull-down assay." (PMID 34680084, 2021). "It has been reported that the enhanced level of HMGB1 ubiquitination may be the causative factor in multiple myeloma (MM)." (PMID 32660524, 2020). "The alkaloid lycorine restores sensitivity to the proteasome inhibitor bortezomib in multiple myeloma by promoting the proteasomal degradation of HMGB1, which in turn inhibits pro-survival autophagy by disrupting the MEK/ERK signaling axis." (PMID 41465435, 2025). "This role extends to chemotherapy, as evidenced in multiple myeloma, where HMGB1 knockdown increased DNA damage markers (γH2A.X) and decreased the key homologous recombination protein Rad51 as well as pro-survival autophagy following dexamethasone treatment." (PMID 41465435, 2025). "In multiple myeloma, it has been shown that High mobility group box protein 1 (HMGB1)-dependent autophagy can contribute to drug resistance." (PMID 37046991, 2023). "Recently, it was reported that USP12, another USP family member, is highly expressed in multiple myeloma cells and binds to HMGB1 to deubiquitinate and stabilize HMGB1, resulting in the promotion of pro-survival autophagy in myeloma." (PMID 36585612, 2022). "Treatment with siRNA against MALAT-1 increased apoptosis of the multiple myeloma tumor cells, which was attenuated by expression of HMGB1." (PMID 34680084, 2021). "HMGB1 also has a novel interaction with the MPM gene, FLT1, shown to be involved in the migration of multiple myeloma cells by associating with β1 integrin, and mediating PKC activation." (PMID 33916178, 2021). "Consistent with CASP1 activation and the ballooning phenotype, a signaling cascade of HMGB1 translocation from the nucleus to the cytoplasm was observed in D089 treated myeloma cells." (PMID 33066043, 2020). "Previous studies suggested that lycorine exerted anti-cancer effects by increasing autophagy, although a recent study reported that lycorine attenuated myeloma growth by inhibiting autophagy through HMGB1 downregulation." (PMID 31901897, 2020). "Human HMGB1 protein produced in mouse myeloma cell line NS0 of eukaryotic cell (Euk-HMGB1) purchased from R&D Systems also bound to C1q in a dose-dependent manner." (PMID 29696019, 2018). "In the context of autophagy, the study of multiple myeloma (MM) showed that USP12 could interact with the key autophagy mediator HMGB1 (high mobility group box-1) protein to deubiquitinate and stabilize it." (PMID 37752518, 2023). "Myeloma cells treated with these PIs also secreted a high level of HMGB1." (PMID 37895838, 2023). "However, the amount of CRT and HMGB1 was highest in PI-treated myeloma cells." (PMID 37895838, 2023). "In multiple myeloma, MALAT1 protects HMGB1 from ubiquitin-mediated degradation, elevating HMGB1 levels to drive autophagy and suppress apoptosis, contributing to resistance to chemotherapeutic agents." (PMID 41465435, 2025). "In multiple myeloma, MALAT-1 increases high mobility group box-1 (HMGB1) to enhance autophagy, hence inhibiting cancer cell death." (PMID 37588204, 2024). "On the other hand, myeloma cells treated with dexamethasone showed little amount of CRT expression and HMGB1 secretion, despite that the cell viability was same as those treated with other drugs." (PMID 37895838, 2023). "Soluble chromatin, released from mouse myeloma nuclei upon micrococcal nuclease digestion, contained mononucleosomes depleted in histone H1 but highly enriched in HMGB1." (PMID 24551219, 2014).
non-alcoholic fatty liver disease (18 papers, 2015 to 2025). "HMGB1 is implicated in the development of non-alcoholic fatty liver Disease (NAFLD) by insulin receptor downstream effectors." (PMID 33912566, 2021). "In adipocytes, c-Jun regulates HMGB1 secretion which bears strong correlation with non-alcoholic fatty liver disease (NAFLD) onset, primarily driven by the downstream effectors of insulin receptor." (PMID 39682695, 2024). "The inflammatory mediator high-mobility group box 1 (HMGB1) plays a critical role in the pathogenesis of non-alcoholic fatty liver disease (NAFLD)." (PMID 26525891, 2015). "From a different perspective, it has been reported that HMGB1 may attenuate non-alcoholic fatty liver disease through activation of the liver x receptor–α-PPARγ pathway, promoting β-oxidation and relieving endoplasmic reticulum stress." (PMID 40362460, 2025). "In nonalcoholic fatty liver disease, OPN promoted macrophage M1 polarization by activation of the JAK1/STAT1/HMGB1 signaling pathway." (PMID 38250077, 2023). "We found that TLR4/MyD88 signaling in liver parenchymal cells plays a pivotal role during the early progression of HFD-induced nonalcoholic fatty liver disease (NAFLD), in which free HMGB1 served as a positive component mediating TLR4 activation." (PMID 34916485, 2021). "HMGB1 was also increased in the plasma in a mouse model of nonalcoholic fatty liver disease (NAFLD) induced by high fat diet and use of HMGB1-neutralizing antibody improved liver inflammation although there was no improvement on liver lipid accumulation." (PMID 33207634, 2020).
septic shock (18 papers, 2007 to 2025). Shock caused by infection; frequently caused by gram negative bacteria, although some cases have been caused by other bacteria, viruses, fungi, and protozoa; characterized by fever, chills, tachycardia, tachypnea, and hypotension. "Analysis of cytokine profiles following treatment revealed significant elevations in IL-6 and IL-10 in anti-HMGB1 pAb-treated mice 24 hours following surgery, which were both associated with survival in the septic shock patient cohort." (PMID 28724977, 2017). "Previous reports have shown that absorption of HMGB‐1 has beneficial clinical effects in patients with septic shock." (PMID 36698511, 2023). "Long-lasting high circulating HMGB1 concentrations have also been reported in human septic patients compared to heathy controls, and patients that died of septic shock had higher HMGB1 levels." (PMID 34208101, 2021). "Analysis of plasma samples obtained from septic shock patients established an association between increased HMGB1 and non-survival, higher APACHE II scores, and increased pro-inflammatory cytokine responses." (PMID 28724977, 2017). "Thus, it suggests that HMGB1 and sRAGE may regulate the inflammatory responses in both term and preterm gestations, and sRAGE can be used as a therapeutic tool, e.g., for LPS-induced septic shock." (PMID 34439812, 2021). "We previously showed a relation between hemodynamic improvement and HMGB-1 in serum levels, and between improvement of respiratory functions and 2-AG and PAI-1 levels in septic shock patients who underwent DHP-PMX." (PMID 20606907, 2010). "In addition, high mobility group box 1 (HMGB1), a late-phase proinflammatory cytokine, which is released from ischemic tissues and septic shock increases serum levels of fetuin-A by 2–3-fold." (PMID 30885236, 2019).